IRF5 (interferon regulatory factor 5)
Diseases named in the same sentence as IRF5 in open-access papers (continued):
Sharing a sentence is not in itself a finding about the gene and the disease.
Autoimmunity (29 papers, 2008 to 2025). The occurrence of an immune reaction against the organism's own cells or tissues. "The prominent role played by IRF5 variants in determining the risk to develop autoimmunity suggests a possible role for IRF5 as modulator of immune responsiveness of melanoma." (PMID 22909381, 2012). "Among these autoimmunity risk genes are IFN regulatory factor 5 (IRF5), which is involved in TLR signaling, and the signal transducer and activator of transcription 4 (STAT4) that interacts with the type I IFN receptor." (PMID 22066971, 2011). "This pre-existing inflammatory state may interact with IRF5 variants to lower the threshold of autoimmunity." (PMID 40869949, 2025). "Although activation of IRF5 in response to a microbial insult can aid in pathogen elimination, the dysregulation of IRF5 activity has been implicated in the pathogenesis of several autoimmune conditions." (PMID 40639948, 2025). "Here we investigated whether polymorphisms in the IRF5 gene would be associated with yet another disease with features of autoimmunity, multiple sclerosis (MS)." (PMID 18285424, 2008). "Since relationships have been observed between development of autoimmunity and responsiveness of melanoma to several types of immunotherapy, we tested whether polymorphisms of IRF5 are associated with responsiveness of melanoma to adoptive therapy with tumor infiltrating lymphocytes (TILs)." (PMID 22909381, 2012). "Genetic risk factors have been newly identified for Sjögren’s syndrome, including IRF5, STAT4, CXCR5, IL12A, HLA-DRA, and BLK, which are linked to autoimmune disorders as well." (PMID 40136761, 2025). "Whereas the activation of IRF5 plays a vital role in both the innate and adaptive arms of the immune system, IRF5 hyperactivation contributes to the development of autoimmunity." (PMID 40639948, 2025). "We then focused on the distinct roles of PTPN22, SLC11A1, and IRF5 in immune regulation and autoimmunity." (PMID 38675400, 2024). "Downstream of TLRs, the adaptor proteins MyD88 and CARD9 and the transcription factor IRF5 generate hyperactivated signaling in LynKO myeloid cells and drive autoimmunity in LynKO mice." (PMID 37265689, 2023). "Further, ICA1 and STAT6 were also closely related to AIRE and IRF5, two very well known autoimmunity genes." (PMID 26031516, 2015). "Recent data regarding the role of IRF5 in both serologic autoimmunity and the overproduction of IFN-α in human SLE are summarized." (PMID 23251221, 2012). "According to recent findings, the IRF5 gene is an important candidate gene in different chronic diseases, especially systemic diseases related to inflammation and autoimmunity." (PMID 20479942, 2010). "Consistent with these in vitro findings, we observed an increase in IRF5 expression in GC B cells in vivo early in disease development, prior to the appearance of overt signs of autoimmunity, with even larger increases evident in plasmablasts and bone marrow plasma cells." (PMID 34197340, 2021). "Here, we evaluated the major SLE risk haplotype of IRF5 on the functional attributes of freshly isolated B cells from human subjects who do not have evidence of SLE or other forms of autoimmunity." (PMID 29867973, 2018). "While reactivation of endogenous retroviral protein expression may elicit serological and cell-mediated responses, an uncontrolled expansion of Treg cells in subjects who lost self-tolerance to IL-2 or IRF5 may explain the development of autoimmunity." (PMID 29379122, 2018). "In addition to its critical role(s) in the regulation and development of host immunity, subsequent studies revealed important roles for IRF5 in autoimmunity, cancer, obesity, pain, cardiovascular disease, and metabolism." (PMID 27481535, 2016). "Interferon Regulatory Factor 5 (IRF-5) is a latent transcription factor involved in autoimmunity." (PMID 25333362, 2014). "Interferon regulating factor 5 (IRF5) is important in autoimmunity and apoptosis in immune cells." (PMID 23251680, 2012).
Autoimmunity (continued). "For example, common IRF5 polymorphisms contribute to the individual variability in the magnitude of cytokine production induced by the NOD2 and TLR ligands in human monocyte-derived DCs, and IRF5 alleles associated with autoimmunity lead to increased cytokine secretion." (PMID 36677464, 2023). "Human and mouse studies strongly support the involvement of both the endosomal TLR7 and TLR9 (TLR7/9) pathways and IRF5 in the pathogenesis of SLE and related autoimmune conditions such as psoriasis and Sjögren’s disease." (PMID 39856058, 2025). "As such, IRF5 has emerged as a therapeutic target for the treatment of SLE and other autoimmune conditions." (PMID 40639948, 2025). "There are some gene variants evaluated to be involved and are common in the pathogenesis of the four diseases of cytokine pathways (e.g., IRF5, STAT4, and TNFSF4) leading to the development of autoimmunity." (PMID 26339139, 2015). "The role of IRF5 in the immune response is not as well established as for other IRFs, but IRF5 has recently received attention in studies on autoimmunity." (PMID 18285424, 2008). "Taken together these findings indicate that the autoimmunity observed across multiple model systems is dependent on a TLR7, MyD88-IRAK4 kinase, and IRF5 dependent signaling cascade, which is independent of NFkB nuclear translocation and cytokine production." (PMID 31354711, 2019).
Obesity (23 papers, 2012 to 2025). Accumulation of substantial excess body fat. "Although its role in obesity-associated inflammation has been described, sex-specific differences in adipose IRF5 expression and its association with immune and metabolic markers remain poorly defined." (PMID 40943154, 2025). "In contrast, overweight and obese females exhibited significantly higher IRF5 transcript levels compared to lean females These findings suggest that IRF5 gene expression is prominently associated with obesity in females." (PMID 40943154, 2025). "This study reveals a differential association of IRF5 with metabolic dysfunction in males versus females despite higher expression in females, particularly in the contexts of obesity." (PMID 40943154, 2025). "Upon diet-induced obesity, mice with a myeloid-deficiency of IRF5 remain insulin sensitive despite increased adiposity." (PMID 32140136, 2020). "Taken together, these data suggest that the obesity-associated changes in adipose expression of IRF5 and TLRs are mutually congruent." (PMID 31718015, 2019). "The elevated expression of IRF5 was found to be associated positively with the clinical indicators of obesity such as BMI and body fat percentage." (PMID 31718015, 2019). "Despite this elevation, IRF5 shows stronger associations with insulin resistance and metabolic dysfunction in men, suggesting sex-specific functional consequences of IRF5 activity in obesity." (PMID 40943154, 2025). "Lastly, despite several lines of evidence implicating IRF5 in metabolic decline associated with diet-induced obesity, the metabolic stressors that induce IRF5 expression remain unknown." (PMID 36042203, 2022). "Interestingly, although the phenotypes of TLR4-deficiency and IRF5-deficiency are near identical under diet-induced obesity, the TLR4-IRF5 axis remains to be experimentally confirmed in the pathogenesis of T2D and its complications." (PMID 32140136, 2020). "Notably, IRF5 has been implicated with macrophage polarization toward an inflammatory M1 phenotype as well as adipose deposition and insulin sensitivity in obesity." (PMID 31718015, 2019). "Here authors show that IRF5 transcriptionally represses the Growth Hormone Inducible Transmembrane Protein gene encoding a mitochondrial protein important for oxidative respiration in macrophages, thus driving the detrimental metabolic changes observed in obesity." (PMID 36042203, 2022). "Since diabetes is a notable obesity complication, we were interested in studying the impact of the observed increase in IRF5 gene on diabetes status of overweight/obese individuals in our cohort." (PMID 40943154, 2025). "IRF5 expression in both overweight (p = 0.031) and those with obesity (p = 0.016) differed significantly from that of NW participants." (PMID 36552771, 2022). "Interferon Regulatory Factor 5 levels have been shown to increase in adipose tissue macrophages in diet-induced obesity." (PMID 36042203, 2022). "In line with the inflammatory signatures, the increased IRF5 expression in the adipose tissue of diabetic obese patients has been suggested as a potential marker for metabolic inflammation in obesity/T2D." (PMID 36360783, 2022). "Consistent with our finding of an increased expression of the mentioned markers, similar changes in the AT expression of MyD88, IRAK1, and IRF5 have been reported in individuals with obesity and/or type-2 diabetes." (PMID 36139454, 2022). "A recent study showed that elevated adipose Irf5 expression in obesity concurs with typical local and systemic inflammatory signatures." (PMID 34922572, 2021). "During obesity, interferon regulator factor 5 (IRF5) regulates the pro-inflammatory polarization of ATM, and deficiency of IRF5 promotes a type 2 immune regulatory environment via ATM-derived transforming growth factor β (TGF-β)." (PMID 34489979, 2021). "The present data show the congruence between adipose tissue expression of IRF5 and most TLRs in obesity/T2D." (PMID 32188105, 2020).
Obesity (continued). "Among the genes, we highlighted the Irf5, which is negatively correlated with insulin sensitivity and obesity, and Alox5ap, which signals adipose tissue inflammation and lipid dysfunction in adipose tissue of obese mice." (PMID 32906847, 2020). "The adipose tissue gene expression of IRF5 correlated positively with clinical indicators of obesity including BMI (r = 0.37, P = 0.008) and body fat percentage (r = 0.51, P = 0.0004)." (PMID 31718015, 2019). "In conclusion, elevated adipose IRF5 expression in obesity concurs with the typical inflammatory signatures, locally and systemically." (PMID 31718015, 2019). "The transcription factor IRF5 is emerging as a new coplayer in the occurrence of obesity complications via its role as an orchestral conductor of macrophage polarization toward an inflammatory phenotype in the obese adipose tissue." (PMID 31718015, 2019). "Dectin-1 requires interferon regulatory factor 5 (IRF5) for immune responses, and IRF5 is necessary for differentiation of M1 AT macrophages, which play a major role in obesity-induced IR." (PMID 28614714, 2017). "Additionally, HOMA-IR emerged as independent predictors, suggesting that IRF5 is closely integrated into the metabolic-inflammatory circuit in male AT, as previously observed in obesity-related insulin resistance." (PMID 40943154, 2025). "Notably, IRF5 directly suppressed TGFB1—a factor promoting tissue remodeling—in adipose tissue macrophages (ATMs), highlighting its role as a checkpoint in obesity-associated inflammation." (PMID 40943154, 2025). "Regarding expression of TLRs, their downstream signaling mediators and IRFs, adipose expression of TLR2 (p = 0.018), TLR3 (p = 0.010), TLR8 (p = 0.048), IRAK1 (p = 0.047), and IRF5 (p = 0.016) was significantly higher in participants with obesity compared to NW participants." (PMID 36552771, 2022). "TLR4, TLR7, and TLR8 are increased in obesity and correlate with IRF5 expression, but whether this occurs in SARS-CoV-2 infection is unknown." (PMID 33936053, 2021). "Next, we wanted to know if IRF5 expression changes in the adipose tissue were consistent with the tissue expression of TNF-α which is a signature inflammatory adipo-cytokine involved in the pathophysiology of obesity/T2D." (PMID 32188105, 2020). "In conclusion, upregulated adipose tissue IRF5 expression in diabetic obese patients concurs with the inflammatory signatures and it may represent a potential marker for metabolic inflammation in obesity/T2D." (PMID 32188105, 2020). "IRF5 orchestrates the macrophage polarization into inflammatory M1 phenotype and it positively modulates the adipose tissue deposition and insulin resistance in obesity." (PMID 32188105, 2020). "Interferon regulatory factor IRF5 is a pro-inflammatory transcription factor, commonly restricted to CD11c+ cells, driving macrophage polarization toward an M1 phenotype, and is notably induced in ATMs in diet-induced obesity." (PMID 32140136, 2020). "Since, in obesity major fat accumulation takes place in the abdominal cavity, i.e., a state of central obesity, IRF5 expression changes in the visceral fat may thus be more relevant to the parameters of BMI and PBF in the obese population." (PMID 32188105, 2020). "The changes in IRF5 expression and their relationship with inflammatory markers in the adipose tissue in obesity remain unclear." (PMID 31718015, 2019). "Interferon regulatory factor (IRF)-5 is known to be involved in M1 macrophage polarization, however, changes in the adipose expression of IRF5 in obesity and their relationship with the local expression of proinflammatory cytokines/chemokines are unknown." (PMID 31718015, 2019). "We wanted to know if adipose CCL5 expression was elevated in obesity and whether these changes correlated with those of IRF5 mRNA expression in the adipose tissue." (PMID 31718015, 2019).
Obesity (continued). "Our IHC and confocal microscopy data support that obesity could play as a positive modulator of IRF5 expression in the subcutaneous adipose tissue in humans as is evident by a higher IRF5 expression in overweight and obese compared with lean individuals." (PMID 31718015, 2019). "HFD also significantly up-regulated Irf5 in the later stages of diet-induced obesity." (PMID 22947075, 2012). "In males, where IRF5 strongly correlates with insulin resistance and metabolic dysfunction, therapeutic approaches that target IRF5 directly or modulate its upstream signaling pathways (e.g., TLR–MyD88–IRAK1) may help mitigate obesity-associated metabolic impairment." (PMID 40943154, 2025). "Thus, adipose IRF5 transcripts in obesity correlate positively with TNF-α, IL-1β, IL-6, CXCL8/IL-8, CXCL9/MIG, CXCL10/IP10, CCL2/MCP1, CCL5, and CCL7/MCP3, all of which can be elevated in COVID-19 “cytokine storm”; positive correlations with IL-2 and IL-12 have been reported by the same group." (PMID 33936053, 2021). "In conclusion, our data show that the AT SRA1 expression correlates with TLRs-3,4,7,9, MyD88, NF-κB, and IRF5 expression in individuals with T2D and with TLR2, IRAK1, and IRF3 expression in individuals with obesity." (PMID 36552771, 2022). "The IRF5-GHITM regulatory axis extends from short- to long-term high-fat feeding and to monocytes and ATMs in patients with obesity and T2D." (PMID 36042203, 2022). "Our data show strong positive correlations between adipose IRF5 gene expression and that of TLR2, TLR7, TLR8, TLR9, MyD88, IRAK-1, and IRF3 in obesity." (PMID 31718015, 2019). "It supports the notion that IRF5 may play a central role in controlling immune and inflammatory responses in the context of obesity, independent of sex-related biological variation." (PMID 40943154, 2025).
atherosclerosis (18 papers, 2012 to 2026). A disease characterized by the build-up of fatty material and calcium deposition in the arterial wall resulting in partial or complete occlusion of the arterial lumen. "In RA, two polymorphisms of IRF5 (rs2004640 GG and rs10954213 GG) revealed a protective effect against the risk of atherosclerosis and cardiovascular disease risk." (PMID 31178872, 2019). "We recently described that IRF5 drives expression of CD11c, a hallmark of a subset of macrophages with a pro-inflammatory role in atherosclerosis." (PMID 29726984, 2018). "A significant loss of CD11c+ macrophages was evident in ApoE-/-Irf5-/- mice in the aorta, draining lymph nodes, and bone marrow cell cultures, indicating that IRF5 maintains CD11c+ macrophages in atherosclerosis." (PMID 28698173, 2017). "Loss of IRF5 expression reduced aortic lesion and necrotic core size in atherosclerosis-prone apolipoprotein E-deficient (ApoE-/-) mice." (PMID 28698173, 2017). "In support of our findings in murine atherosclerosis, a significant association between IRF5 and CD11c expression was also found in human atherosclerotic tissue (Figure VIIA in the online-only Data Supplement)." (PMID 28698173, 2017). "Our data indicate that CD11c expression is the hallmark of an IRF5-dependent subset of macrophages with a detrimental role in atherosclerosis." (PMID 28698173, 2017). "In the present study, we evaluated the effect of IRF5 deficiency on the development of atherosclerosis in 2 complementary murine models." (PMID 28698173, 2017). "In this context, the results of a recent study of individuals diagnosed with RA revealed an association between the IRF5 rs2004640 polymorphism and subclinical atherosclerosis." (PMID 25011482, 2014). "The authors proposed that defactinib is an attractive molecule for repurposing to treat patients with UC or other inflammatory conditions, such as arthritis, acute lung injury, or atherosclerosis, in which IRF5 function in macrophages has been intimately linked to pathogenicity." (PMID 41007813, 2025). "Irf5 knockdown prevents the aggravation of atherosclerosis in Aff3ir-ORF2 deficient mice." (PMID 40315012, 2025). "Next, we sought to explore whether the expression of IRF5 and CD11c was associated with plaque inflammation and size of the necrotic core in human atherosclerosis." (PMID 35567557, 2022). "As IRF5 and CD11c were strongly associated with plaque rupture in human atherosclerosis, we aimed to explore whether IRF5 deficiency would reduce plaque rupture frequency." (PMID 35567557, 2022). "Likewise, mice deficient in IRF5 presented increased atherosclerosis and also exhibited hyperlipidemia, increased adiposity, and insulin resistance compared to WT controls." (PMID 31178872, 2019). "IRF5 in macrophages directly regulates CD11c to impair efferocytosis and consequently worsen the atherosclerosis." (PMID 38175709, 2024). "ITGAX and CCR1 were identified as potential biomarkers for atherosclerosis, while macrophage-related genes, including ITGAX/CD11c and interferon regulatory factor 5, are strongly associated with symptomatic carotid artery disease." (PMID 39845786, 2024). "Our study progresses our knowledge on IRF5 in atherosclerosis towards translation by offering validation of IRF5 as a potential therapeutic target in human CVD." (PMID 35567557, 2022). "The top enriched pathway was ‘dendritic cells function in atherosclerosis’ (P = 0.002) when IRF5 was present." (PMID 35567557, 2022). "Our data indicate that IRF5 is a key regulator of efferocytosis and necrotic core formation in atherosclerosis." (PMID 28698173, 2017). "Our data reveal that IRF5 deletion has a significant effect on macrophage phenotype and function in atherosclerosis." (PMID 28698173, 2017). "IRF5 is detrimental in atherosclerosis by promoting the maintenance of proinflammatory CD11c+ macrophages within lesions and controlling the expansion of the necrotic core by impairing efferocytosis." (PMID 28698173, 2017).